CXCL10 (C-X-C motif chemokine ligand 10)
Diseases named in the same sentence as CXCL10 in open-access papers (continued):
Sharing a sentence is not in itself a finding about the gene and the disease.
infection (continued). "Interestingly, and as observed after infection of mice with H. pylori, the expression of the chemokines CXCL9 and CXCL10 was strongly reduced in BCG-infected BATF3-deficient compared to WT mice, whereas CXCL11 expression was unaffected by the BCG infection or the mouse genotype." (PMID 31188899, 2019). "We hypothesized that GP63 would continue to be able to suppress CXCL10 through both stages of infection, as transcriptomics indicate GP63 expression during both stages while microarray expression analysis and proteomics have identified GP63 in lesion derived amastigotes." (PMID 31440475, 2019). "In contrast, CXCL10 protein showed a negative association with FVC independently of infection." (PMID 30463560, 2018). "Finally, throughout all infection groups, the frequencies of CXCL10 were reduced after treatment." (PMID 30619332, 2018). "Furthermore, most of the pro-inflammatory genes found on this array, which we have previously identified to be increased with 22L infection (such as Cxcl10, Ccl8, Tnf, IL1a, and IL1b), were similarly increased in the absence of TLR2 or C5aR1 signaling during scrapie infection." (PMID 30596651, 2018). "However, the rate of migration of sensory and motor Fbs was suppressed by CXCL10-siRNA infection." (PMID 30686982, 2018). "Prior to infection, investigation of the expression of key macrophage differentiation markers indicated that (unstimulated) iPSDMs expressed low to very low levels (0.1–5 counts per million (c.p.m.)) of M1 markers (CXCL10, CXCL11 and TAP1) and also modest levels (10–1,000 c.p.m)." (PMID 28440293, 2017). "Also, high systemic CXCL10 levels before infection were revealed to be associated with rapid HIV progression, and the level of systemic CXCL10 during primary HIV infection is positively associated with HIV DNA levels and viral load and negatively associated with CD4+ T cell count." (PMID 29085362, 2017). "Therefore, CXCL10 is also recognized as a biomarker that predicts severity of various infections." (PMID 28018321, 2016). "Additionally, there was a trend, though it was not statistically significant, of higher relative levels of expression of IL-10 and CXCL10 mRNAs in the nonlymphoid epithelium and follicle-associated epithelium of cattle that had cleared the infection." (PMID 27147736, 2016). "Here, we gained insights on the association between a pro-inflammatory chemokine, CXCL10/IP-10 and HIV infection in four cohorts of HIV+ individuals, studied at distinct stages of infection (before, primary and chronic stage with spontaneous- and treatment-controlled infection)." (PMID 27509048, 2016). "Interestingly, CXCL10 blockade during infection resulted in significantly reduced peripheral parasitaemia, suggesting that the absence of this chemokine has a beneficial effect for the development of parasite-specific responses involved in the control of parasite replication." (PMID 24476686, 2014). "Consistent with that concept, the increased resistance to infection observed in the absence of CXCL10-mediated cell trafficking was found to be associated with a preferential accumulation and subsequent expansion of parasite-specific CD4+ T cells in spleens of infected animals." (PMID 24476686, 2014). "When stimulated through the Fas pathway, HSV-2 infected macrophages do not only undergo apoptosis but may also up-regulate the production of TNF-α, CXCL9 and CXCL10 - chemo-attractants for activated T cells and NK cells necessary to eradicate local infection and inflammation." (PMID 23922974, 2013). "Indeed, we have found that mice receiving subcutaneous injections of CXCL10 (100 ng) at days 1, 3, and 7 of infection with L. amazonensis have attenuated cutaneous lesions, as well as a 7- and 3.5-fold increase in IFN-γ and IL-12 production in re-stimulated lymph node cells." (PMID 23801993, 2013).
infection (continued). "Thus, we analyzed whether NiV-infection induces production of CXCL10 in vivo, using the hamster animal model, which closely reproduces human infection and induces lethal outcome starting from day 5 p.i.." (PMID 22393386, 2012). "Finally, we showed intense staining for CXCL10 in the brain of patients who succumbed to lethal NiV infection during the outbreak in Malaysia, confirming induction of this chemokine in fatal human infections." (PMID 22393386, 2012). "Interestingly, the proinflammatory response of supernatants from HIV-1-infected macrophages on day 16 after infection showed marked increases in CXCL10, MCP-1, and TNF-α by Bioplex array, while other cytokines and chemokines were not significantly changed (data not shown)." (PMID 23078780, 2012). "CXCL9 and CXCL10 play an important role in regulating NK cell and T lymphocyte influx to the site of infection and for control of vaginal HSV infection; therefore, modulated production of specific chemokines may be imperative for future vaccine adjuvant candidates." (PMID 23062757, 2012). "Also, CXCL-10 is specific for effector T-cell recruitment during infection and, therefore, its deletion reduces T-cell trafficking, which enhances production of CD4+CD25+Foxp3+ and suppressive cytokines interleukin-10 (IL-10) and tumor growth factor- β1 (TGF-β1)." (PMID 21439091, 2011). "The enhanced and early production of CXCL10 that we observe in Mtb-infected IL-10−/− mice may contribute to the increased number of IFN-γ-producing CD4+ T cells recruited to the lungs, in keeping with the known role of CXCL10 in Th1 migration during other infections." (PMID 20518032, 2010). "Infection of rhesus (Macaca mulatta) or cynomolgus (Macaca fascicularis) macaques with pathogenic SIV leads to the induction of multiple inflammatory chemokines in lymph nodes and spleen including: CXCL8; CXCL9, CXCL10, and CXCL11; CCL3, CCL4, CCL5; CCL2; CCL19; and CCL20." (PMID 19149556, 2009). "Thus, because of its unique appearance early after infection of the pancreas, CXCL10 might be a prime target for a therapeutic neutralization." (PMID 23675028, 2007). "In urine, we found increases in IL-1RA, G-CSF, and chemokines CXCL10, CCL4, CCL11, GROα/β/γ, and IL-8/CXCL8, with IL-1RA and CCL4 showing direct correlation with the degree of pyuria at the time of infection." (PMID 41810365, 2026). "Surprisingly, some antiviral cytokines are elevated between week 5 and 12 post-infection including CXCL-1 and CXCL-10." (PMID 41516418, 2026). "RT-qPCR analysis of RNA isolated from hGBOs at 48 h post-infection revealed a robust upregulation of IFNB1 and IFNB1-stimulated IFIT1, MX1, CXCL10, and OAS1." (PMID 41255708, 2025). "During early-phase infection, there was robust upregulation of pro-inflammatory cytokines such as JUN, IL15, ATF2, TNFSF15, and CXCL10, indicating strong immune activation." (PMID 40649996, 2025). "In infected digitoxin-treated cells, IFN-β, CXCL-10, IL-1β, and IL-8 levels are significantly reduced, suggesting that nuclear α3 modulates IE1-PML early during infection." (PMID 40143325, 2025). "In both the B.1.351 model and the AAV-hACE2-WA1 model, intranasal SARS-CoV-2 infection resulted in increases in pro-inflammatory cytokines (e.g., IL-1β, IFNβ, CXCL10, IFNγ, IL-6, and CCL11) in the hippocampus and cerebrospinal fluid at 7 days post-infection." (PMID 39861887, 2025). "In contrast, untreated infection networks were dominated by inflammatory mediators (IL6, CXCL10, CCL2, VCAM1, SELE) and antiviral sensors (DDX58, OAS1, IFI44, IFI6), which reflect strong cytokine and interferon-driven immunity." (PMID 41480150, 2025). "Cxcl10, co-regulated by MyD88/NF-κB and IRF3, recruits CD8+ T cells and NK cells to infection sites, such as vaccine injection sites." (PMID 40573198, 2025). "The levels of CXCL10/IP-10 and IL-15 in BAL fluid peaked in both the lean and obese groups during the acute phase of infection, with CXCL1-/IP-10 levels exhibiting the most dramatic increase." (PMID 40027795, 2025).
infection (continued). "In HCMV-infected digitoxin-treated cells, the mRNA levels of NF-κB, interferon-β (IFN-β), CXCL-10, IL-1 β, and IL-8 were reduced, suggesting that CGs target the PML-IE1 complex via the α3 isoform in the early stages of infection, resulting in HCMV inhibition." (PMID 40143325, 2025). "CXCL6 and CXCL10 both belong to CXCL chemokine family, which primarily attract the neutrophils and T cells to sites of inflammation, infection, and trauma, respectively." (PMID 40224485, 2025). "We tested the extent to which astrocyte infection with SARS-CoV-2 would alter Wnt/β-catenin pathway activity, production of Wnt ligands, and production of the chemokine CXCL10." (PMID 41156605, 2025). "Among these proteins, in particular, TLR3 activated MSCs secreted TNFSF10, CXCL10, ISG15 and C2 (green highlight, 7C) were found upstream of several affected immune response and infection pathways in all 3 cell types." (PMID 40861855, 2025). "Mast-cell-derived cytokines and chemokines facilitate the migration of dendritic cells (DCs; TNF-α and CCL20) and effector T cells (CXCL10/IP10 and CCL5/RANTES) to the infection site and draining lymph nodes." (PMID 40867663, 2025). "The selective effect of TLR4 knockout on HMPV-mediated TNF was further reflected at the protein level: secreted TNF was significantly reduced at 20 h post-infection in TLR4 KO cells, while secretion of the IFN-inducible chemokine CXCL10 remained unchanged." (PMID 41346628, 2025). "For example, IFN-γ enhances macrophage antimicrobial function via JAK-STAT1 activation and induces CXCL9/CXCL10 expression, recruiting CXCR3+ T cells to infection sites." (PMID 41007639, 2025). "For the cell host response in the early-phase infection, genes such as JUN, IL15, ATF2, TNFSF15, and CXCL10 were significantly upregulated, reflecting a strong pro-inflammatory and immune response." (PMID 40649996, 2025). "We found that infection with all strains of Ot upregulated the expression of IL-6, TNF-alpha, IL-1ß, and CXCL-10 (human macrophages only) both in the presence and absence of IFN-γ." (PMID 40587585, 2025). "Treatment with KLRE effectively controlled the infection by reducing IFN-γ levels, which inhibited CXCL10 production, highlighting its role in promoting cell-mediated immunity against parasites like Trypanosoma cruzi." (PMID 40313946, 2025). "Real-time PCR analysis of mRNA from whole brain tissue revealed elevated expression of proinflammatory mediators ll-6, Il-1β, Ccl2, Cxcl9, and Cxcl10 in both the WT and eNOS+/− mice 3 days post-MA10 infection." (PMID 40573374, 2025). "Since BBB integrity is disrupted and CXCL10 levels are induced in COVID-19/Long COVID, we assessed the impact of SARS-CoV-2 direct infection on the Wnt/β-catenin pathway." (PMID 41156605, 2025). "Similar to what we observed with poly(I:C) stimulation, the NEMO-KD cells were still able to mount a full induction of IFIT1 and CXCL10 expression upon HAV infection, with only a slight decrease for CXCL10 at 48 h post infection." (PMID 39853114, 2025). "In neonatal Swiss mice, USUV infection led to an increase in typical neuroinflammatory cytokines, including IL-6, CCL3, CCL4, CCL5, CXCL9, and CXCL10, with CXCL10 being upregulated to the highest level in this model." (PMID 39907280, 2025). "Top downregulated DEGs in bystander cells indicated a decreased enrichment of certain pro-inflammatory cytokines and signaling molecules in ADE compared to conventional infection conditions, including CXCL11, CXCL10, CCL2, DOCK4, STAT1, and JAK2." (PMID 39902963, 2025). "In the case of MHV-JHM infection, changes in expression (from 0% to 100%) were visible in IL-6, IL-18, IL-33, ENA-78 (CXCL5), GRO alpha (CXCL1), IP-10 (CXCL10), MCP-1 (CCL2), MIP-1 beta (CCL4), MIP-2 alpha (CXCL2), RANTES (CCL5), and TNF alpha." (PMID 40358160, 2025). "The majority of post‐COVID‐19 proteome studies show a similar trend of lower concentrations of CXCL10 and CXCL9 after infection, even in long‐COVID‐19 patients." (PMID 40949320, 2025).
infection (continued). "Although brain inflammation was limited in our model, cytokines, including G-CSF, CXCL10, CXCL1, IL-6, and IL-1β, were already increased in the periphery by day 3 post-infection, despite a low to undetectable viral load." (PMID 41472308, 2025). "Consistent with clinical observations, in vitro infection of RD cells and in vivo infection of suckling mice in our study similarly demonstrated significant upregulation of IL-6, TNF-α, CXCL2, CXCL3, CXCL8 (IL-8), and CXCL10." (PMID 40872743, 2025). "Several cytokines (TNF, IL-1β) and chemokines (CXCL10, CCL2, CCL5) were reduced in the brains of Rag1–/– animals at day 14 after infection, which were restored or exceeded WT levels mainly with Th1 adoptive transfer, whereas Th17 cells were less effective." (PMID 39989461, 2025). "Lower CXCL10 levels may potentially result in reduced recruitment of these immune cells to the airway epithelium, leading to an inadequate immune response to inflammation or infections, thereby prolonging the oxidative stress triggered by nano- and microplastics." (PMID 40298680, 2025). "Of these, CCL20, CXCL10, CXCL1, CXCL8, and IL-18 showed higher levels compared to uninfected epithelium 24 h after infection." (PMID 40586572, 2025). "Five days after infection, the gene expression of ISG15, CXCL-10, and OASL2 was significantly induced by virus (Online Resource 1D)." (PMID 39821815, 2025). "Secreted CCL3, CCL4, CCL5, CXCL10, IFN-γ, IL-10, and VEGF were also significantly elevated in LCLs but at lower levels than in de novo infection." (PMID 40359016, 2025). "IP-10, also known as CXC ligand 10 (CXCL10), is part of the innate immune response and functions in drawing leukocytes to sites of infection." (PMID 41444685, 2025). "CXCL10 and CXCL8 and CCL-5 are proinflammatory chemokines that play critical roles in the pathogenesis of infection, and function as prognostic indicators of coronaviruses severity." (PMID 40181980, 2025). "For example, TYROBP, CCR7, CXCL10, and CXCL11 emerged as top DEGs in both infected and bystander cells in ADE compared to conventional infection." (PMID 39902963, 2025). "The genes that reached statistical significance at any time point during infection were IFN-β and CXCL10." (PMID 40666984, 2025). "The capacity of early and mature retinal organoids to respond to T. gondii tachyzoite infection was determined by RT-qPCR for human cytokine transcripts CCL2, CXCL8, CXCL10, and interleukin-6 (IL6)." (PMID 40137771, 2025). "Key inflammatory cytokines and acute-phase mediators (CXCL10, SAA3, THBS4) are down-regulated immediately upon infection, alongside TGFB2, low-density lipoprotein receptors, structural constituents and adhesion factors." (PMID 39863683, 2025). "The observed infiltration of immune cells after infection with swH1N1 agrees with the upregulation of chemotactic factors (AMCF-II, CXCL8/IL8, CXCL2, CXCL10, and CCL20) and their receptors (CCR1 and CXCR2) at the transcriptional level." (PMID 39247193, 2024). "Although visually, CXCL10 and TNF levels also appeared lower after the third infection, we were unable to detect a statistically significant difference, potentially because of the small sample size." (PMID 39666392, 2024). "Upon infection with Sendai virus (SeV), ectopic overexpression of EGLN1 significantly induced the expression of IFN-β, CXCL10, and CCL5 in HEK293T cells." (PMID 38670937, 2024). "Chemokines (CCL2, CCL3L1, CCL4, CXCL9, CXCL10, CXCL11, and XCL1) were also significantly upregulated after infection." (PMID 38698849, 2024). "Nectin-1 was redistributed, at the protein level, in adjacent uninfected cells surrounding infection, inducible by CCL3, IL-8 (or CXCL8), and possibly CXCL10 and IL-6, thus facilitating spread." (PMID 38857290, 2024). "As expected, we observed an increase in neutrophil, monocyte, and NK cell recruitment cytokines CXCL10, CCL5, and IL-15 during SEOV infection in Cas9 WT control HUVEC." (PMID 39585900, 2024).
infection (continued). "In the milk, during infant infection, CCL20 and CXCL10 concentrations were greater in Group I than in Group C, and CXCL10 was the only chemokine that increased in the mother’s serum during infant infection." (PMID 39867906, 2024). "In our study on the early infection phase of FHV-1, the upregulation of CCL17, CCL20, and CXCL10 among these cytokines and chemokines, as well as that of TNF were observed, while there were no significant changes in IFNs." (PMID 39591303, 2024). "Group I showed greater numbers of all CCR6+ B-cell subsets and CXCR3+ naive B cells and plasma cells than did Group C. Infection of the nurslings promoted increased CCL20, CXCL10, IL-6, IL-8, total IgA, and IgG levels in the milk." (PMID 39867906, 2024). "On the other hand, the STAT1–STAT1 complex formation was actually increased by PRVABC59 infection, leading to upregulated IFN-γ stimulated genes including the pro-inflammatory cytokine CXCL10." (PMID 39057782, 2024). "Whilst concentrations of MMP-9 and CCL2 were reduced upon infection, IFN-β and CXCL10 were induced as the infection course progressed, with significant increases over mock after 48 hpi and 72 hpi for both the USUV- and WNV-infected conditions." (PMID 40295794, 2024). "As effector cells, NK cells are recruited to the site of infection by chemokines secreted by macrophages, such as CXCL9 and CXCL10, which are produced in response to infection." (PMID 39770782, 2024). "Our studies revealed an increase in TLR3 expression and phosphorylation of NF-κB following RRV and Ro1845VP4-G446R infection, as well as an increase in the cytokines CXCL9 and CXCL10." (PMID 38860860, 2024). "Infection of BRB with ZIKV leads to the generation of IL-1β, IL-6, IFN-α, IFN-β, TNF-α, CCL5 and CXCL-10." (PMID 39795906, 2024). "After infection, TLR3 expression and p-NF-κB levels increased in cholangiocytes, leading to increased release of CXCL9 and CXCL10." (PMID 38860860, 2024). "With respect to the female response to infection-induced neuroinflammation, there was significant upregulation in the expression of CXCL9, CXCL10, BDNF, IL-13 and KCNN4 in the medulla oblongata." (PMID 38879567, 2024). "Following the apical infection of hBLEC with both RVFV strains, we observed upregulation of three inflammatory cytokines, i.e., CCL5, CXCL9, and CXCL10, in the apical compartment." (PMID 39345143, 2024). "Despite BA.4 and BA.5 replicating similarly to BA.2 in HAEs, we consistently observed reduced innate activation, measured by ISG induction, after BA.4 and BA.5 infection (IFNB, CXCL10, IFIT1, IFIT2, DDX58 and RSAD2)." (PMID 38228858, 2024). "CXCL10 and CXCL11 highlight the proactive immune response by drawing immune cells to infection or inflammation sites." (PMID 38957806, 2024). "IL-8 and CCL3 were produced at significantly increased levels compared to mock infection, with trends for IL-6, CXCL1, and CXCL10, at 12 h post-infection." (PMID 39599904, 2024). "IFNB and CXCL10 gene induction, normalized to GAPDH, were similar after Alpha ΔOrf6 and WT infection, despite lower E RNA levels for Alpha ΔOrf6, consistent with increased innate immune induction by the deletion virus." (PMID 38228858, 2024). "Immune response genes such as the pro-inflammatory cytokine CXCL10, IFI27, USP18, IFIT1, and RSAD2/Viperin were shared between both in vivo infection times and A549 cells." (PMID 39065267, 2024). "Infection of the cornea with ZIKV leads to the synthesis of the IL-1β, TNF-α, CCL5, and CXCL-10 which recruits other cells of the immune system to the cornea and this promotes inflammation and damage to corneal tissue leading to keratitis." (PMID 39795906, 2024). "IP-10 (CXCL10), TNF-α, and IL-6 were significantly upregulated in response to Delta infection, with concentrations of 3,236, 25.73, and 1,391 pg/mL, respectively." (PMID 38568894, 2024).